CD4 (CD4 molecule)
Diseases named in the same sentence as CD4 in open-access papers (continued):
Sharing a sentence is not in itself a finding about the gene and the disease.
autoimmune disease (continued). "Notably, in autoimmune disorders CD4+/CD25+/FoxP3+ dependent suppression of effector cells (macrophages, natural killer, dendritic, and cytotoxic T cells) was reported." (PMID 28902871, 2017). "The role of antigen-specific activation of CD4+ helper T cells and downstream activation of effector mechanisms such as autoantibody production by B cells in the pathogenesis of a number of autoimmune diseases such as RA and Sjögren’s syndrome is well established." (PMID 28769925, 2017). "However, some studies have shown that patients with autoimmune diseases have less effective or fewer CD4+CD25highFoxp3+ Treg cells compared with healthy individuals [reviewed in Ref." (PMID 29123529, 2017). "Taken together, these results suggest that NTP may be used in treatment of CD4+ T cell-mediated autoimmune diseases such as psoriasis." (PMID 29138509, 2017). "Furthermore, depletion of TGFBR2 specifically in CD4+ T cells leads to early onset lethal autoimmune disease, further substantiating the anti-inflammatory role of TGFβ." (PMID 27270652, 2017). "ASM activities and signaling may provide potential alternatives to current therapeutic approaches to control CD4+ T-cell responses, and may help to design new strategies for treatment of human autoimmune diseases." (PMID 28749465, 2017). "In mice, overexpression of the miR-17~92 cluster has been shown to be associated with an increased CD4+ T cell population and autoimmune disease; however, similar data is not available for humans." (PMID 29657261, 2016). "The immunosuppressive potential of these cells was solidified in the result that replacement of the CD25+ fraction of CD4+ T cells could limit autoimmune disease induction." (PMID 27656181, 2016). "Alterations in the cTfh compartment have been found in several ab-mediated autoimmune diseases, like SLE and RA, in which the expansion of cTfh cells (defined as CD4+CXCR5+PD-1+ICOS+ T cells) could be linked to disease activity." (PMID 26872212, 2016). "Importantly, PBC is a complex autoimmune disease involving autoreactive CD4+ and CD8+ T cell responses, present in human circulating lymphocytes and liver, B cell compartment, and innate immunity, including macrophages." (PMID 26150899, 2015). "Activation of CD4+ T-helper cells is critical for the control and elimination of invading pathogens, however, autoimmune disease might arise if CD4+ T cells become activated in response to self-antigens." (PMID 25964886, 2015). "Recently, a new subset of CD4+T helper cell termed Follicular helper T cells (Tfh), which play a pivotal role in B cell activation and differentiation in lymphoid structures, has been reported to participate in some certain autoimmune diseases." (PMID 25889760, 2015). "CD4-AsiCs bearing siRNAs or shRNA targeting RORγt might suppress Th17 differentiation and treat Th17-mediated autoimmune diseases." (PMID 26792955, 2015). "Thus, in order to treat Th17-mediated autoimmune disorders, it is necessary to develop a specific strategy to only inhibit RORγ/RORγt transcriptional activity in immune cells, especially CD4+ T cells." (PMID 26792955, 2015). "The potentiation of TCR-stimulated IL-2 transcription that results from blocking Gβγ in CD4+ T helper cells could have applications for autoimmune diseases." (PMID 25629163, 2015). "In conclusion, we have demonstrated that latent infection with γ-herpesviruses predisposes individuals to severe autoimmune disease by modulating DCs and suppressing Treg frequencies likely through DC modulation (CD40 expression) and this in turn, exaggerates CD4+ and CD8+ T cell aggression." (PMID 26356194, 2015). "Thus, it is of interest to explore the use of CD4-AshR-RORγt chimeras in animal and clinical trials of autoimmune diseases." (PMID 26792955, 2015). "These animal studies suggested calcitriol may inhibit autoimmune disease at least in part through a VDR-dependent action on CD4+ T cells to induce IL-10-producing Treg cells." (PMID 25852682, 2015).
autoimmune disease (continued). "This raises the intriguing possibility that miR-31 may be preferentially diminished in Treg cells and its upregulation in CD4+ T cells under inflammatory stress may limit pTreg cell induction in human autoimmune diseases." (PMID 26165721, 2015). "Therefore, here we analyzed the anti-CD4 mAb BT-061 (Tregalizumab), which currently is under development for the treatment of autoimmune diseases such as rheumatoid arthritis and psoriasis." (PMID 26670584, 2015). "Indeed, of the 144 hypomethylated genes in African-American naïve CD4+ T cells, 18 and 27 have been previously related to lupus and autoimmune diseases, respectively." (PMID 26609326, 2015). "However, interest in GADD45A has remained in the autoimmune diseases because it is overexpressed in CD4 T cells of SLE patients, correlating with global and site-specific DNA hypomethylation in these cells." (PMID 26330155, 2015). "Th17 cells, a particular subset of CD4+ cells and their respective cytokines, play a pivotal role in the inflammatory response and autoimmune diseases and also direct the defense against bacterial and fungal infections of the gastrointestinal tract, skin, airways and lungs." (PMID 26174551, 2015). "Autoimmune diseases can be prevented by reconstitution with CD4+CD25+ cells in animal models." (PMID 26564056, 2015). "Summary of main conclusions regarding vitamin D, CD4+ T lymphocytes, and autoimmune disease." (PMID 25852682, 2015). "CD4 TEM cells have been recently involved in contributing to autoimmune diseases such as experimental autoimmune encephalomyelitis in mice, autoimmune diabetes, rheumatoid arthritis and systemic lupus erythematosus, although the antigen specificity of these cells is not clearly defined." (PMID 25803808, 2015). "Nor, in contrast to a recent report on antigen + adjuvant induced autoimmune diseases, could we demonstrate differences in the Th17 population—either the fraction of CD4+ cells expressing IL-17A or its expression level." (PMID 25407682, 2014). "Low levels of NKG2D+CD4+ T cells are present in healthy individuals, but this population may be expanded in some chronic and autoimmune diseases." (PMID 25286418, 2014). "Similarly, expanded CD4+ T-cell populations are also documented in patients with various autoimmune diseases, including RA, MS, and Wegener's granulomatosis." (PMID 24967373, 2014). "Because CD4+T cells play a critical role in the development of autoimmune diseases, including BD, we further tested whether there was a direct effect of FICZ and ITE on cytokine production using purified CD4+T cells." (PMID 25045206, 2014). "These two kinds of CD4+T cells have opposite roles in the development of autoimmune diseases." (PMID 25429429, 2014). "Moreover, we show that while CTLA-4, but not IL-10, plays a role in the induction of Foxp3 expression in naive CD4+ T cells, the latter is important for iTreg cell-mediated protection from autoimmune disease." (PMID 25238105, 2014). "Notably, the frequency of cytopenias and autoimmune disorders appeared to be much lower in CD4+/TCRαβ+ T-LGL leukemia as compared with other types." (PMID 24413066, 2014). "CD4+CD25+Foxp3+ Tregs account for 5%-10% of the CD4+ T cell panel in healthy human and mice, which are sufficient to play an important role in the maintenance of immune homeostasis and the limitation of autoimmune disease." (PMID 25475342, 2014). "The hypothesis of MS as a T cell-mediated autoimmune disease is supported by the fact that adoptive transfer of activated myelin-specific CD4+ T cells can induce EAE." (PMID 25374694, 2014). "Although low CD4 count has been associated with autoimmune disease, it has not been described with Kikuchi-Fujimoto disease." (PMID 25313340, 2014). "To test whether Shcbp1 might play a role in vivo in T cell effector responses in the context of autoimmune disease, we chose to use the CD4 T cell driven experimental autoimmune encephalomyelitis (EAE) model." (PMID 25153088, 2014).
autoimmune disease (continued). "Besides Th1 cells, some other subsets of CD4+T cells participate in the process of several autoimmune diseases, such as Th17 cells and Treg cells." (PMID 25429429, 2014). "AHA is characterized by the presence of an autoimmune mechanism that alone or accompanied by autoimmune disease, aging, pregnancy, or drug exposure causes breakdown of immune tolerance to FVIII associated with CD4 T-cells and results in development of autoantibodies against FVIII." (PMID 24741588, 2014). "CD28null cells have also been reported in autoimmune disease where CD4 + CD28null cells were not susceptible to the regulatory effects of regulatory T cells, results similar to our own unpublished findings." (PMID 24885856, 2014). "It has already been shown that CD4+CD25+FOXP3+ play a protective role in autoimmune disease." (PMID 24995020, 2014). "Although inflammatory Th17 CD4+ T cells mediate diverse autoimmune diseases, and HFD predisposes autoimmune diseases such as trinitrobenzene sulfonic acid (TNBS) colitis and experimental autoimmune encephalomyelitis (EAE), Th17 CD4+ T cells are not involved in the inflammation of obese mice." (PMID 23781214, 2013). "As a model to mimic the clinical features of SQM in human patients, Aire KO mice spontaneously develop CD4+ T cell-mediated autoimmune disease that provokes severe KCS (middle) with progressive keratinization and corneal opacification (right) noted by 8 - 10wks of age." (PMID 24143217, 2013). "The role of CD4+CD25+ cells in the regulation of autoimmune diseases has been widely described." (PMID 23738007, 2013). "EAE is considered predominantly a CD4 mediated disease and further studies are required to dissect how autophagy in T cells influences the onset or progression of autoimmune diseases in animal models and if these roles of autophagy are also dependent on cell survival." (PMID 23596443, 2013). "CD4+ T cells are the main effectors in most autoimmune diseases." (PMID 23575112, 2013). "Follicular helper T cells (TFH) represent a distinct subset of CD4+ T cells specialized in providing help to B lymphocytes, which may play a central role in autoimmune diseases having a major B cell component such as systemic lupus erythematosus." (PMID 24069401, 2013). "Numerous studies in animal models of autoimmunity showed that defects in CD4+CD25+Foxp3+ cells can contribute to the development of autoimmune diseases and that these diseases could be reversed by the adoptive transfer of Treg cells." (PMID 24187560, 2013). "In a number of conditions including infections, autoimmune diseases, and allergic reaction, the host generates an effector CD4+ T cell response of inadequate phenotype that may lead to worsening of symptoms and often to exacerbation of the disease." (PMID 23966946, 2013). "Although the distinct CD4+ helper T cell subset is famous for IL-17 producing cells (known as Th17), several innate immune cells have recently been reported to secrete IL-17 in inflammatory or autoimmune diseases." (PMID 23671588, 2013). "The mechanisms by which MHC molecules control autoimmunity are still not understood but recent advances in the molecular characterization of peptide-MHC complexes targeted by autoreactive CD4+ T cells in type 1 diabetes (T1D) and other autoimmune diseases have shed some light on this issue." (PMID 23850635, 2013). "Thus, conditional deletion of TGFβ1 expression in CD4+ and CD8+ T-cells (by crossing mice carrying a conditional floxed allele of TGFβ1 with mice expressing CD4-Cre) resulted in age-related autoimmune disease, characterised by T-cell activation and colitis." (PMID 22902140, 2012). "Follicular helper T (Tfh) cells are recognized as a distinct CD4+ helper T-cell subset, which provides for B-cell activation and production of specific antibody responses, and play a critical role in the development of autoimmune disease." (PMID 22649468, 2012).
autoimmune disease (continued). "Collectively, mTEC and thymic monocyte/dendritic cells play a crucial role in establishing self-tolerance by eliminating autoreactive T cells (negative selection) and/or by producing immunoregulatory FOXP3+ T cells, which prevent CD4+ T cell-mediated organ-specific autoimmune diseases." (PMID 22876245, 2012). "Given that T09 is such a potent inhibitor of disease onset and progression in several models of autoimmune disease, we questioned whether T09 inhibited the differentiation and function of other CD4+ T cell subsets, specifically TH1, TH2, and iTreg cells." (PMID 23029557, 2012). "Patients with autoimmune diseases have high CD4+/CD8+ ratio in their blood, indicating that imbalance between T lymphocyte subclasses could impair the immune system and result in diseases." (PMID 20008077, 2011). "Recently, however, a novel subpopulation of memory CD4+ T-lymphocytes has been identified that produces high levels of IL-17, which plays a major role in the induction of inflammation and tissue destruction in various autoimmune disorders." (PMID 19622600, 2011). "CD4+ T cells have been shown to be involved in autoimmune diseases including VKH syndrome." (PMID 21297967, 2011). "CD7- T-cells may also play a role in autoimmune disease evidenced by the increased CD4+CD7- cell expansion and accumulation reported in rheumatoid arthritis and psoriasis." (PMID 22126605, 2011). "It will be important to determine whether inhibitory KIRs play a similar role in enhancing CD8+ and possibly CD4+ T cell-mediated immunity to other pathogens and in autoimmune disease." (PMID 22022261, 2011). "It is likely that Th17 may also be involved in the adoptive-transfer-mediated change in the CNS, given that IL17-producing CD4+ T-cells have been shown to play a fundamental role in different models of autoimmune diseases." (PMID 20637096, 2010). "CD4+CD28null T-cells from patients with autoimmune diseases or other chronic immunologic disorders have abnormal productions of various cytokines that may have potential importance in disease pathogenesis." (PMID 20126467, 2010). "Self-reactive T cells sometimes escape thymic clonal deletion, and can subsequently provoke autoimmune diseases such as type 1 diabetes (T1D) unless they are controlled by a network of tolerance mechanisms in the periphery, including CD4+ regulatory T cells (Treg) cells." (PMID 21059266, 2010). "Interestingly, HLA-DQA2 is known to be involved in pro-inflammatory CD4(+) T-cell-mediated autoimmune diseases such as MS and type 1 diabetes." (PMID 20426824, 2010). "The increased proliferation of CD4+CD25low T cells may play a role in vivo and explain the existence of this expanded T-cell subset in autoimmune disease patients." (PMID 21151941, 2010). "We reported that autoimmune disease in gp130 mutant mice is caused by increased homeostatic proliferation of CD4+ T-cells, which is due to elevated production of IL-7 by non-hematopoietic cells as a result of IL-6 family cytokine-gp130-STAT3 signaling." (PMID 19228423, 2009). "In HIV, the risk of developing autoantibodies and autoimmune disease depends on the time in the disease course and may be stratified by HIV manifestations, CD4 count and HIV viraemia." (PMID 19830165, 2009). "However, data pointing to a secondary effect on CD4+CD25high regulatory T cells in autoimmune disorders have also emerged." (PMID 19046457, 2008). "In the present study using a murine model, we demonstrated the potential of a new therapeutic approach for markedly reducing the progression of organ-specific autoimmune diseases through the efficient accumulation of chemokine receptor-expressing CD4+CD25+ regulatory T cells in target organs." (PMID 17284325, 2007). "Thus, it seems likely that therapy using antigen-specific CD4+CD25+ regulatory T cells has the most potential for treatment of autoimmune diseases in which target antigens have been identified." (PMID 17284325, 2007).
autoimmune disease (continued). "Similarly, administration of CD4+ T helper cell peptide in IFA intraperitoneally can inhibit onset of CD4 T cell dependent autoimmune disease." (PMID 18000535, 2007). "Regulatory CD4+CD25+ T cells have been implicated in a number of pathologic processes including elevated levels of Treg cells in certain types of cancer and infectious diseases, and reduced Treg levels in autoimmune diseases." (PMID 16579866, 2006). "Indeed, transfer of a subset of adult CD4+CD8-CD25+ thymocytes (natural regulatory T or Treg cells) into day 3 thymectomized mice prevents autoimmune disease." (PMID 16579866, 2006). "Interestingly, this pattern may be reversed in autoimmune disorders, where overactivated immune cells like CD4+ T cells and B cells that resist ferroptosis may exhibit enhanced pathogenicity and contribute to tissue damage." (PMID 41154692, 2025). "The immunology of most autoimmune diseases (e.g., rheumatoid arthritis or inflammatory bowel disease, IBD) is complex and not very well understood, and better tools are needed to study the different immune cell subsets implicated in disease initiation and progression, such as CD4+ T cells." (PMID 40775564, 2025). "While CD4+ T helper (Th) cells protect against infection, certain subsets, such as CD4+IL−17a+ T cells, can trigger a decrease in barrier integrity, and autologous T cells attack self−tissues; however, regulatory T (Treg) cells play a major role in regulating autoimmune disease." (PMID 40702356, 2025). "Experimental autoimmune encephalomyelitis (EAE) is a T cell‐mediated autoimmune disease model that closely replicates a significant proportion of the pathological features observed in MS, including demyelination, blood–brain barrier disruption, and the infiltration of myelin‐specific CD4+ T cells." (PMID 40765112, 2025). "Therefore, the expansions of cTph cells (defined as CXCR5−PD‐1hi CD4+ T cells) reported in patients with autoimmune diseases could potentially reflect a more heterogeneous T‐cell response." (PMID 40538220, 2025). "In addition, a novel function of CD4+ IELs in the production of DEFA5 was discovered, indicating that CD4+ T lymphocytes may adopt new roles in the context of certain autoimmune diseases." (PMID 41050652, 2025). "In addition, MG is thought to be an autoimmune disease dependent on CD4+ T cells." (PMID 41488644, 2025). "Furthermore, we provide new insights and theoretical foundations for diseases targeting CD4+T cell subsets aging as a treatment focus, offering novel approaches for therapy, especially in infections, cancers, autoimmune diseases, and other diseases in the elderly." (PMID 39155409, 2024). "Additionally, a low CD4/CD8 ratio has been associated with poor prognosis in various infectious and autoimmune diseases, highlighting the need for careful monitoring and potentially more aggressive immunomodulatory treatments to restore immune balance and improve patient outcomes." (PMID 39224609, 2024). "Analysis of autoimmune disorders has revealed that CD8 T regulatory cells (CD8 Tregs) inhibit pathogenic responses through recognition of self-peptides associated with MHC class Ia or class Ib (MHC-E: mouse Qa-1 and human HLA-E) expressed by target CD4+ T helper cells." (PMID 37934601, 2024). "Additionally, another study constructed CD8 T cells expressing the HLA-DR1 CAR, which led to a reduced CD4 T cell response and inhibition of autoantibody production, indicating the potential for a highly specific therapeutic approach in the treatment of autoimmune diseases." (PMID 39676874, 2024). "Moreover, CD4+ iTregs can be induced in vitro from CD4+ Tconvs under specific culture conditions and these cells are currently being tested in clinical trials as potential autologous cell therapy for patients affected by several autoimmune diseases." (PMID 38203623, 2023).